TEFM (transcription elongation factor, mitochondrial)
Description:
Transcription elongation factor which increases mitochondrial RNA polymerase processivity. Regulates transcription of the mitochondrial genome, including genes important for the oxidative phosphorylation machinery.
Synonyms: C17orf42; FLJ22729; COXPD58
Tractability: Small molecule: a structure with a bound ligand is known. PROTAC: ubiquitination databases record sites on it; its protein half-life has been measured.
Gene: Protein-coding gene on chromosome 17 (30,897,336 to 30,906,249, reverse strand). Ensembl gene ENSG00000172171.
Subcellular location: Mitochondrion matrix; Mitochondrion matrix, mitochondrion nucleoid
Subcellular location (Human Protein Atlas): Mitochondria
Gene Ontology:
Molecular function: crossover junction DNA endonuclease activity; protein binding; RNA binding; transcription elongation factor activity; nucleic acid binding
Biological process: mitochondrial DNA replication; positive regulation of mitochondrial transcription; regulation of oxidative phosphorylation; transcription elongation by mitochondrial RNA polymerase
Cellular component: mitochondrial matrix; mitochondrial nucleoid; mitochondrion; ribonucleoprotein complex
Genetic constraint (gnomAD): Loss-of-function variants: 16 observed, 30.08 expected, observed/expected ratio (o/e) 0.53, 90% interval 0.36 to 0.81. The upper end of that interval is the gene's LOEUF score, 0.81, which puts it in group 3 of 6, group 1 being the genes least tolerant of losing a copy. Missense variants: 382 observed, 440.92 expected, observed/expected ratio (o/e) 0.87, 90% interval 0.8 to 0.94. Synonymous variants: 155 observed, 166.58 expected, observed/expected ratio (o/e) 0.93, 90% interval 0.82 to 1.06.
Homologues: Orthologues: chimpanzee TEFM (99% identical), macaque TEFM (94% identical), pig TEFM (78% identical), dog TEFM (76% identical), rabbit TEFM (76% identical), guinea pig TEFM (71% identical), rat Tefm (67% identical), mouse Tefm (67% identical), tropical clawed frog tefm (45% identical), zebrafish tefm (44% identical), Drosophila melanogaster CG14450 (20% identical).
Diseases named in the same sentence as TEFM in open-access papers:
TEFM is named in the same sentence as 18 diseases in open-access papers, as found by Europe PMC text mining. Sharing a sentence is not in itself a finding about the gene and the disease. The quoted sentences say what the papers report.
hepatocellular carcinoma (3 papers, 2021 to 2024). A malignant tumor that arises from hepatocytes. "Additionally, TEFM was found to enhance the growth and spread of hepatocellular carcinoma (HCC) by facilitating the transition from the G1 to S phase." (PMID 39507532, 2024). "Our bioinformatics analysis of TCGA data revealed an aberrant over-expression of TEFM in hepatocellular carcinoma (HCC)." (PMID 33771980, 2021).
breast carcinoma (1 paper, 2021). "Using mass spectrometric analyses, we found that most elevated proteins in Ki8751-treated cancers were all mitochondrial proteins, namely NDFIP1, CLK1, and TEFM, suggesting that Ki8751 treatments may enhance mitochondrial biogenesis of breast cancer cells." (PMID 33628590, 2021).
cardiomyopathy (1 paper, 2024). A disease of the heart muscle or myocardium proper. "Like POLRMT and TEFM, MRPP3/PRORP and ELAC2 are essential proteins with non-redundant functions that cause very early cardiomyopathy and premature death in mice that model that seen in the patient mutations." (PMID 38779771, 2024).
colorectal cancer (1 paper, 2021). A primary or metastatic malignant neoplasm that affects the colon or rectum. "Furthermore, we showed that TEFM promoted HCC metastasis by inducing EMT, which is consistent with another study of TFAM in the promotion of colorectal cancer (CRC) cells." (PMID 33771980, 2021).
congenital myasthenic syndrome (1 paper, 2023). Congenital myasthenic syndrome (CMS) is a group of genetic disorders of impaired neuromuscular transmission at the motor endplate characterized by fatigable muscle weakness. "The responsiveness of these patients to salbutamol, a drug commonly used to alleviate symptoms of fatigable muscle weakness in the Congenital Myasthenic Syndromes (primary disorders of the NMJ), suggests an involvement of TEFM in neuromuscular structure or function." (PMID 36823193, 2023).
glioma (1 paper, 2021). A benign or malignant brain and spinal cord tumor that arises from glial cells (astrocytes, oligodendrocytes, ependymal cells). "Similar to the functions of TEFM in HCC, another mitochondrial transcription regulator TFAM also has been reported to induce G1 cell cycle transition, but inhibit cell apoptosis in glioma and non-small cell lung cancers." (PMID 33771980, 2021).
Mitochondrial myopathy (1 paper, 2023). "We report for the first time that TEFM variants are associated with mitochondrial respiratory chain deficiency and a wide range of clinical presentations including mitochondrial myopathy with a treatable neuromuscular transmission defect." (PMID 36823193, 2023).
cancer (2 papers, 2021 to 2024). A tumor composed of atypical neoplastic, often pleomorphic cells that invade other tissues. "Consistently, TEFM expression was significantly higher in cancer tissues compared to normal lung tissues." (PMID 39075464, 2024). "We initially analyzed the mRNA levels of TEFM using The Cancer Gene Atlas (TCGA) database and observed significantly elevated expression of TEFM in LUAD tissues compared to normal lung tissues in both unpaired and paired samples." (PMID 39075464, 2024).
tumor (2 papers, 2019 to 2021). "We showed also that TEFM expression was positively associated with tumor size and vascular invasion, as well as poor patient survival in HCC." (PMID 33771980, 2021). "The expression of miR-194-5p was negatively associated with TEFM expression in tumor tissues from 30 HCC patients (r = −0.493, p = 0.012)." (PMID 33771980, 2021). "Up-regulation of TEFM was observed in 83% (25/30) tumor tissues compared with their peritumor tissues." (PMID 33771980, 2021). "The expression of TEFM was further analyzed by qRT-PCR in paired tumor and peritumor tissues from 30 HCC patients." (PMID 33771980, 2021). "In keeping with the expression at mRNA, TEFM expression at protein level was also elevated in tumor tissues compared with peritumor tissues." (PMID 33771980, 2021). "Mechanistically, TEFM exerts its tumor growth and metastasis promoting effects at least partly through increasing ROS production and subsequently by activation of ERK signaling." (PMID 33771980, 2021). "In the present study, we observed that TEFM expression is significantly increased in HCC tumor tissues and cell lines mainly due to the down-regulation of miR-194-5p." (PMID 33771980, 2021). "IHC staining confirmed a significant decrease of TEFM in tumor tissues from shTEFM group than those from shCtrl group, implying that the tumor-suppressive effect was exerted by TEFM knockdown." (PMID 33771980, 2021). "TEFM knockdown dramatically inhibited tumor formation and growth ability of SNU-354 cells in vivo." (PMID 33771980, 2021).
TEFM also shares sentences with these, for which no sentence is quoted: developmental delay (2 papers); autosomal dominant progressive external ophthalmoplegia (1); Childhood onset (1); epilepsy (1); Epileptic encephalopathy (1); Intellectual disability (1); lactic acidosis (1); mitochondrial encephalomyopathy (1); neurological disease (1).